CCT3 (chaperonin containing TCP1 subunit 3)
Description:
Component of the chaperonin-containing T-complex (TRiC), a molecular chaperone complex that assists the folding of actin, tubulin and other proteins upon ATP hydrolysis. The TRiC complex mediates the folding of WRAP53/TCAB1, thereby regulating telomere maintenance. As part of the TRiC complex may play a role in the assembly of BBSome, a complex involved in ciliogenesis regulating transports vesicles to the cilia.
Synonyms: TCP-1-gamma; CCTG; TRIC5; CCT-gamma; NEDSVH; PIG48
Tractability: Small molecule: a structure with a bound ligand is known. Antibody: the Human Protein Atlas places it where antibodies can reach. PROTAC: UniProt records ubiquitination sites on it; ubiquitination databases record sites on it; its protein half-life has been measured.
Target class: Enzyme; Hydrolase
Gene: Protein-coding gene on chromosome 1 (156,308,960 to 156,367,873, reverse strand). Ensembl gene ENSG00000163468.
Subcellular location: Cytoplasm
Subcellular location (Human Protein Atlas): Cytosol; Plasma membrane; Vesicles
Pathways (Reactome):
Metabolism of proteins: Association of TriC/CCT with target proteins during biosynthesis; Cooperation of PDCL (PhLP1) and TRiC/CCT in G-protein beta folding; Folding of actin by CCT/TriC; Formation of tubulin folding intermediates by CCT/TriC; Prefoldin mediated transfer of substrate to CCT/TriC
Organelle biogenesis and maintenance: BBSome-mediated cargo-targeting to cilium
Gene Ontology:
Molecular function: protein binding; protein folding chaperone; RNA binding; ATP binding; ATP hydrolysis activity; ATP-dependent protein folding chaperone
Biological process: positive regulation of protein localization to Cajal body; positive regulation of telomerase RNA localization to Cajal body; positive regulation of telomere maintenance via telomerase; protein folding; protein stabilization
Cellular component: chaperonin-containing T-complex; extracellular exosome; microtubule; cytoskeleton; cytosol; cell body; cytoplasm; zona pellucida receptor complex
Genetic constraint (gnomAD): Loss-of-function variants: 9 observed, 55.75 expected, observed/expected ratio (o/e) 0.16, 90% interval 0.096 to 0.28. The upper end of that interval is the gene's LOEUF score, 0.28, which puts it in group 1 of 6, group 1 being the genes least tolerant of losing a copy. Missense variants: 588 observed, 690.94 expected, observed/expected ratio (o/e) 0.85, 90% interval 0.8 to 0.91. Synonymous variants: 205 observed, 239.12 expected, observed/expected ratio (o/e) 0.86, 90% interval 0.76 to 0.96.
Homologues: Orthologues: chimpanzee CCT3 (99% identical), macaque CCT3 (99% identical), rabbit CCT3 (98% identical), dog CCT3 (98% identical), guinea pig CCT3 (97% identical), mouse Cct3 (97% identical), rat Cct3 (96% identical), pig CCT3 (91% identical), tropical clawed frog cct3 (87% identical), zebrafish cct3 (86% identical), Drosophila melanogaster CCT3 (70% identical), Caenorhabditis elegans cct-3 (61% identical). Paralogues in human: TCP1 (33% identical), CCT4 (31% identical), CCT7 (31% identical), CCT5 (30% identical), CCT2 (28% identical), CCT8 (27% identical), CCT6B (26% identical), CCT6A (26% identical), PIKFYVE (26% identical), CCT8L2 (22% identical), MKKS (20% identical), HSPD1 (20% identical), and 1 more.
Diseases named in the same sentence as CCT3 in open-access papers:
CCT3 is named in the same sentence as 71 diseases in open-access papers, as found by Europe PMC text mining. Sharing a sentence is not in itself a finding about the gene and the disease. The quoted sentences say what the papers report.
hepatocellular carcinoma (20 papers, 2016 to 2025). A malignant tumor that arises from hepatocytes. "CCT3 has been involved in mitosis progression and associated with poor prognosis in hepatocellular carcinoma, has been implicated in osteosarcoma tumorigenesis, and appeared as a candidate biomarker in epithelial ovarian cancer and in cholangiocarcinoma patients." (PMID 29954368, 2018). "For example, there is a significant difference in the expression of TCP1/CCT2/CCT3/CCT4/CCT5/CCT6A/CCT7/CCT8 in hepatocellular carcinoma." (PMID 37058032, 2023). "Research: Hepatocellular carcinomaAchievement: CCT3 supports proper mitotic progression and cell proliferation in hepatocellular carcinoma cells." (PMID 36185198, 2022). "Abnormal expression of CCT3 significantly reduced the overall survival (OS) of hepatocellular carcinoma (HCC) patients." (PMID 36313331, 2022). "Research: hepatocellular carcinomaAchievement: CCT3 predicts poor prognosis in hepatocellular carcinoma." (PMID 36185198, 2022). "CCT3 is highly expressed in hepatocellular carcinoma (HCC) tissues and promotes the tumorigenesis of HCC." (PMID 35773623, 2022). "Previous studies have reported the inhibition of CCT3 expression can suppress the proliferation of various cancer cells, such as papillary thyroid carcinoma, gastric carcinoma, breast cancer and hepatocellular carcinoma." (PMID 34505628, 2021). "In various cancers, the expression levels of different CCT subunits were upregulated in varying degrees: CCT3 in hepatocellular carcinoma, and CCT8 in hepatocellular carcinoma and glioblastoma." (PMID 33869000, 2021). "For instance, CCT8 regulates cell proliferation, migration and invasion in several tumors; CCT2 inhibition reduces cell migration in tubulin-binding agent-resistant tumors; and CCT3 supports cell proliferation in hepatocellular carcinoma." (PMID 33917510, 2021). "For instance, CCT3 overexpression was proposed to predict poor prognosis in patients with hepatocellular carcinoma." (PMID 34612768, 2021). "Previous studies reported that the expression levels of different CCT subunits were upregulated in various cancers, such as CCT2 in prostate, breast, and lung cancers, CCT3 in hepatocellular carcinoma (HCC), and CCT8 in HCC and glioblastoma." (PMID 33815471, 2021). "More recent studies have shown CCT subunit 3 (CCT3) upregulation in hepatocellular carcinoma (HCC), cholangiocarcinoma and colon cancer, and that overexpression of CCT3 in HCC patients is associated with poor prognosis." (PMID 29340068, 2017). "Clinically, overexpression of CCT3 predicts poor prognosis in hepatocellular carcinoma patients after hepatectomy." (PMID 27818681, 2016). "Different studies have previously linked expression levels of different CCT subunits in various cancers, such as CCT2 in prostate, breast and lung cancers and CCT3 in hepatocellular carcinoma (HCC)." (PMID 37667113, 2024). "It is worth noting, however, that silencing CCT3 could also cause S phase arrest in breast cancer cells and hepatocellular carcinoma cells without any additional treatments." (PMID 34612768, 2021). "In conclusion, CCT3 is involved in the carcinogenesis and progression of HCC and serves as a potential therapeutic target and biomarker in hepatocellular carcinoma." (PMID 36185198, 2022). "CCT3 is indispensable for hepatocellular carcinoma (HCC) cell proliferation." (PMID 31501420, 2019). "For example, CCT3 and CCT8 were overexpressed in hepatocellular carcinoma (HCC) and the proteins were detected in the plasma from patients, suggesting that CCT3 could be used as a biomarker for screening HCC." (PMID 29299146, 2017). "Through analysis of the GSE144269 transcriptomic dataset, we found that CCT3 expression is significantly higher in hepatocellular carcinoma tissue compared to adjacent non-cancerous tissue, consistent with previous research findings." (PMID 39210442, 2024).
hepatocellular carcinoma (continued). "The mRNA and protein expression of CCT3 in hepatocellular carcinoma (HCC) tissues are higher than those in non-HCC tissues." (PMID 36185198, 2022). "The expression of CCT3 is increased both at mRNA and protein level in hepatocellular carcinoma (HCC) tissues than those in non-HCC tissues, and CCT3 involves in carcinogenesis and development of HCC and has prognostic indication in HCC." (PMID 34505628, 2021). "In hepatocellular carcinoma (HCC), circ-CCT3 sponges miR-378a-3p restoring fms-related receptor tyrosine kinase 1 (FLT1) expression and accelerating HCC progression." (PMID 41153715, 2025). "Research: The non-malignant liver tissues.Achievement: CCT3 may represent targets in the progression of hepatocellular carcinoma." (PMID 36185198, 2022). "Finally, CCT3 knockdown could reduce both total and phosphorylated STAT3 levels in hepatocellular carcinoma HepG2 cells." (PMID 34612768, 2021). "The mRNA and protein expression of CCT3 in hepatocellular carcinoma (HCC) tissues are higher than those in non-HCC tissues, and CCT3 plays an important role in the tumorigenesis and progression of HCC and has prognostic value in HCC." (PMID 32518527, 2020).
breast carcinoma (18 papers, 2020 to 2025). "Currently, the chaperonin containing TCP-1 subunit 3 (CCT3) subunit has been linked to several malignancies, including breast cancer, lung cancer, gastric cancer, liver cancer, and cervical cancer." (PMID 39928781, 2025). "Both the mRNA and the protein levels of CCT3 are potential diagnostic biomarkers and therapeutic targets for breast cancer." (PMID 36185198, 2022). "In addition, CCT3 gene was positively associated with high expression of MYC in breast cancer, which was also consistent with our findings in Hallmark analysis." (PMID 34505628, 2021). "Research: Breast cancerAchievement: Suppression of CCT3 inhibits the proliferation and migration in breast cancer cells." (PMID 36185198, 2022). "Overexpression of NFκB rescued the effect of CCT3 on the proliferation and migration of breast cancer cells." (PMID 36185198, 2022). "CCT3 supported breast cancer cell proliferation through the nuclear accumulation of β-catenin, perhaps directly since signals from CCT3 and β-catenin co-localized in the nucleus." (PMID 35602608, 2022). "CCT3 was significantly upregulated in a large proportion of human breast cancer tissues, and its overexpression was also significantly correlated with breast cancer clinical characteristics, including the clinical stage and the TNM classification." (PMID 36185198, 2022). "Another study demonstrated that knockdown of CCT3 blunted the proliferation and migration of breast cancer cells by inhibiting NF-κB signaling." (PMID 35773623, 2022). "At present, there are many researches on CCT3 in liver cancer, breast cancer, lung cancer, and so on." (PMID 36185198, 2022). "They confirmed that the knockdown of CCT3 can induce apoptosis in breast cancer with the annexin method in this study." (PMID 36185198, 2022). "Secondly, down regulation of CCT3 significantly inhibited NF-κB activity and reduced the proliferation and metastatic capacity of breast cancer cells." (PMID 36185198, 2022). "Overexpression of NF-κB reversed the inhibitory effect of CCT3 silencing on breast cancer cell proliferation and migration." (PMID 35773623, 2022). "Similar to CCT3, overexpression of CCT6A has been found in many malignancies, including liver cancers as well as breast cancer and lung cancer, and is associated with clinical prognosis and TNM stage." (PMID 34676169, 2021). "In our study, we found that knockdown of CCT3 can inhibit the proliferation and metastasis of breast cancer cells, induce apoptosis and regulate the cell cycle." (PMID 32518527, 2020). "The results showed that overexpression of NFκB rescued the effect of CCT3 on the proliferation and migration of breast cancer cells." (PMID 32518527, 2020). "In our study, we also found that knockdown of CCT3 inhibited the migration of breast cancer cells through Transwell analysis." (PMID 32518527, 2020). "MTT assay and Celigo analysis showed that knockdown of CCT3 inhibited the proliferation of breast cancer cells, which is consistent with reports in other tumours." (PMID 32518527, 2020). "Lentivirus expressing short hairpin RNA targeting CCT3 mRNA (shCCT3) was used to infect the breast cancer cell lines HCC1937 and MDA-MB-231." (PMID 32518527, 2020). "In the present study, we found that knockdown of CCT3 inhibits the proliferation and metastasis of breast cancer cells and that the mechanism is probably related to regulation of the cell cycle, apoptosis and several signal transduction pathways." (PMID 32518527, 2020). "In our study, we found that transduction with the lentiviral shRNA targeting CCT3 suppressed the mRNA and protein expression of CCT3 in the breast cancer cell lines HCC1937 and MDA-MB-231." (PMID 32518527, 2020). "We confirmed that knockdown of CCT3 can induce apoptosis in breast cancer with the annexin method in this study." (PMID 32518527, 2020). "A rescue experiment showed that overexpression of NFκB-p65 rescued the cell proliferation and migration affected by CCT3 in breast cancer cells." (PMID 32518527, 2020).
breast carcinoma (continued). "Furthermore, CCT3 knockdown significantly reduced Wnt signaling in breast cancer cells and increased miR-223 expression." (PMID 39928781, 2025). "The knockdown of CCT3 inhibited proliferation, metastasis, and apoptosis of breast cancer cells, and the mechanism may be related to the regulation of the cell cycle, apoptosis, and multiple signal transduction pathways." (PMID 36185198, 2022). "CCT-3 may promote breast cancer tumorigenesis at least in part via activating the Wnt/β-catenin signaling pathway." (PMID 36185198, 2022). "For instance, CCT3 inhibitor inhibited the proliferation and migration in breast cancer." (PMID 36313331, 2022). "Furthermore, the proliferation and colony formation of gastric and breast cancer cells were significantly suppressed upon CCT3 knockdown in vitro and in vivo." (PMID 34612768, 2021). "Likewise, CCT3 depletion suppressed breast cancer cell proliferative and metastatic capacities, and ultimately induced apoptosis." (PMID 34676169, 2021). "CCT3 is closely related to the proliferation and migration of breast cancer and may be a novel therapeutic target." (PMID 32518527, 2020). "In future studies, rescue experiments of other signal transduction protein and mechanism studies will be carried out to confirm the role of these signal transduction pathways in breast cancer and to explore the mechanism between CCT3 and signal transduction pathways." (PMID 32518527, 2020). "Therefore, we tried to explore other signalling pathways found that CCT3 can regulate a variety of signalling pathways in breast cancer cells, some of which play an important role in tumour development." (PMID 32518527, 2020). "CCT3 expression was knocked down by transfecting breast cancer cells with lentiviral shRNA." (PMID 32518527, 2020). "Knockdown of CCT3 promoted apoptosis in the breast cancer cell lines HCC1937 and MDA-MB-231." (PMID 32518527, 2020). "Apoptosis analysis showed that knockdown of CCT3 induced apoptosis in breast cancer cells." (PMID 32518527, 2020). "A positive regulatory loop may exist between CCT3 and miR-223 in breast cancer." (PMID 36313331, 2022). "However, the role of CCT3 in breast cancer is still unclear." (PMID 32518527, 2020). "Celigo image cytometry assay and MTT assay showed that the proliferation of the breast cancer cells was inhibited significantly in KD + Control cells compared to control cells, and overexpression of NFκB-p65 in KD cells (KD + OE group) rescued the effect of CCT3." (PMID 32518527, 2020). "For example, CCT2, CCT3, CCT4, and CCT5 were increased in breast cancer cells and positively correlated with tumor progression." (PMID 40374617, 2025). "Currently, extensive research has been conducted on CCT3 in HCC, lung cancer, breast cancer, cervical cancer, and MM." (PMID 39928781, 2025). "However, whether CCT3 regulates the development of breast cancer is still unknown." (PMID 32518527, 2020). "A systematic analysis of protein half-lives in MCF-7 breast cancer cells found, in contrast, that CCT4 had the longest half-life (∼10.6 h), followed by CCT8, CCT7 and CCT2, with half-lives between 7–8 h, and CCT5 and CCT3 with the shortest half-lives of 4.6 and 2.5 h, respectively." (PMID 35602608, 2022). "To this end, we found that CCT2 protein levels, but not CCT3 as example, varied among breast cancer cell lines, with highest levels of CCT2 in TNBC cells and lowest in luminal A types and non-transformed breast epithelial cells (CCT3 shown as a representative of other subunits)." (PMID 31964905, 2020). "Genomic analysis of the Cancer Genome Atlas, which contains data for 971 cases of breast carcinoma with sequencing and copy number analysis, showed that 51% of cases have alterations in at least one CCT subunit and that the highest alteration rate occurred in CCT3 (31%)." (PMID 32518527, 2020).
breast carcinoma (continued). "Moreover, we noted that CCT3 mRNA and protein in our study did not vary substantially between the lentiviral control and CCT2-FLAG overexpressing breast cancer cells." (PMID 33996588, 2021).